IGF1R (insulin like growth factor 1 receptor)
Diseases named in the same sentence as IGF1R in open-access papers (continued):
Sharing a sentence is not in itself a finding about the gene and the disease.
cancer (continued). "Although some trials of IGF-1R targeting agents have shown safety issues or limited efficacy, it is hoped that further investigation into this strategy of combining anti-cancer drugs with agents that inhibit IGF/IGF-1R signaling will yield effective treatment for HBV-associated HCC." (PMID 33669204, 2021). "While no recurrent cancer-specific mutations of IGF1R or its ligands have been described to date, studies have provided evidence for a link between this signaling pathway and the risk of developing cancer." (PMID 34191793, 2021). "Finally, the role of nuclear InsR/IGF1R in cancer biology is of exceptional translational relevance." (PMID 33918477, 2021). "However, despite preclinical efficacy of experimental IGF1R TKIs, most clinical trials reported an insignificant cancer curative value (e.g., dalotuzumab, robatumumab, R1507, figitumumab)." (PMID 34209513, 2021). "A wealth of evidence suggests an important role for IGF-1R signaling in many cancers." (PMID 34611148, 2021). "Therefore, further studies investigating the safety and efficacy of combining an IGF1R inhibitor with BRAF and MEK inhibitorsare warranted in cancers harboring BRAF mutations and resistant to targeted therapies." (PMID 34831014, 2021). "Understanding differences between InsR and IGF1R signaling may aid the development of cancer therapeutics." (PMID 34191793, 2021). "IGF1R also plays an important role in promoting cancer metastasis as reviewed." (PMID 33429867, 2021). "Our findings provide clues on the correlation between IGF-1/IGF-1R expression and cancer immunity and suggest that it could be a potential predictive maker of the efficacy of immunotherapy." (PMID 34804946, 2021). "Typically, high expression level of IGF-1 and IGF-1R was detected in most malignant tumors." (PMID 34804946, 2021). "Consequently, PKM2 knockdown inhibits the activation of AKT, the key downstream effector of IGF-1R signaling, and increases apoptotic cancer cell death during hypoxia." (PMID 34359752, 2021). "They suggest that co-targeting of the FGFR axis may potentiate the anti-cancer effect of IGF-1R inhibiting drugs." (PMID 33916323, 2021). "Collectively, these results suggest that decorin may act as a natural antagonist of the IGF1R and IR-A in bladder and other types of cancer where these receptors might play a critical role." (PMID 33673232, 2021). "Also, IGF1R inhibitors are suggested as anti-cancer drugs because of their effects on proliferation inhibition." (PMID 35095996, 2021). "IGF1R has been investigated as a therapeutic target in treating cancer for decades." (PMID 33429867, 2021). "Notably, discoidin domain receptor 1 (DDR1), a collagen receptor often dysregulated in cancer, is involved in a functional crosstalk and feed forward loop with both the IR-A and the insulin like growth factor receptor 1 (IGF1R)." (PMID 34206590, 2021). "Moreover, the SNAI2 oncogene was identified as a target gene for nuclear IGF1R action, with potentially important consequences in cancer invasion and metastasis." (PMID 33918477, 2021). "The current status of IGF-1R molecular imaging in cancer was previously reviewed." (PMID 34209513, 2021). "Thus, the identification and characterization of novel regulators and binding partners of the IGF1R represents an emerging areas of cancer research." (PMID 33673232, 2021). "We hypothesize that the contribution of the IR/IGF1R-axis to PDAC cancer growth experiences a self-limitation either by the local destruction of pancreatic islets via local destructive growth or by the surgical removal of the primary cancer." (PMID 34638472, 2021). "The influence of IGF-1R signaling after radiation may influence cancer cell survival due to alterations in apoptotic response." (PMID 35008602, 2021).
cancer (continued). "In this review we will initially cover some general aspects of IGF action and regulation in cancer and then focus in particular on the role of transcriptional regulators and novel interacting proteins, which functionally contribute in fine tuning IGF1R signaling in several cancer models." (PMID 33673232, 2021). "Fusion-derived antigens and CD 99 or IGF1R expression could be potential targets for cancer vaccines or CAR-T therapy." (PMID 33801953, 2021). "Signaling pathways activated by IGF1/IGF1R respond to radiotherapy in several types of cancer." (PMID 34178997, 2021). "Therefore, defining the mechanism by which IGF-1R expression is regulated in cancer cells will inform the design of cancer treatment aimed at targeting aberrant IGF signaling." (PMID 34359752, 2021). "These MCF-7 cancer cells overexpress IGF-1R, which might lead to more binding of vimentin to the cell membrane, and a block (i.e., decreased permeability) of the paracellular junctions." (PMID 34299089, 2021). "Secondly, though IGF-1 and IGF-1R share the same signaling pathway, whether they have different prognostic and immunologic values in different types of cancer needs further investigation." (PMID 34804946, 2021). "Given that percental proportions of each staining category varied within one given sample, cancer cells with a weak membranous IGF1R immunostaining (m-IGF1R 1+) were detected in 123 (76.9%) and cancer cells with a strong membranous immunostaining (m-IGF1R 2+) were seen in 91 (56.9%) of all samples." (PMID 34638472, 2021). "Reportedly, circRNAs mainly work as miRNA sponges to adsorb miRNAs and modulate targetgenes’ expression, thereby exerting either pro- or anti-cancer effects.Circ_0000517 is reported to modulate the expression levels of IGF1R andSMAD6 via sponging miR-326 in HCC." (PMID 34837683, 2021). "IGF-1R is thought to be overexpressed in several cancer types." (PMID 34681810, 2021). "The correlation between IGF-1, IGF-1R, and cancer immunity was explored." (PMID 34804946, 2021). "In this mini review, we discuss a symbiotic relationship between the clocks and cancer as well as its relation with cancer-related metabolic pathways such as IGF-1R/mTOR/Akt signaling that could drive tumorigenesis." (PMID 33672910, 2021). "IGF1R has been revealed to regulate cancer cell invasion and migration in multiple human cancers." (PMID 34185427, 2021). "Similarly, human cancer converged at the Hif-2α oncogenic axis has been suggested to require IGF-1R activation." (PMID 34381769, 2021). "Cancer-associated fibroblasts stimulate an EMT-driven gain of cancer stemness through a paracrine interplay between CAFs and prostate cancer cells, and also constitute a supporting niche for cancer stemness in lung cancer through a paracrine IGF-II/IGF1R signaling." (PMID 34660589, 2021). "IGF-1R signaling plays an important role in a variety of human cancers." (PMID 34359714, 2021). "IGF-1R is expressed significantly more in African American normal tissue, compared with that of Caucasian patients, and specifically more in the breast tissue, with increased dysregulation in cancers." (PMID 35008602, 2021). "Whether daintain/AIF-1 regulates cancer stemness in HCC through IGF/IGF-1R signaling is still unknown." (PMID 33669204, 2021). "In addition, IGF1R activation determines phosphorylation and nuclear translocation of STAT3, which modulates transcriptional activation of cancer-associated genes." (PMID 33673232, 2021). "Interestingly, anti-IGF1R therapies (cixutumumab) or radiotherapy can promote an immune-suppressive microenvironment due to IGF2- or CAF-dependent IGF1 release from cancer cells." (PMID 34065119, 2021).
cancer (continued). "Clinical and laboratory data argue that targeting Type I IGF receptor (IGF1R) alone may be insufficient to disrupt this pathway as the insulin receptor (IR) may also be a relevant cancer target." (PMID 33429867, 2021). "The prognostic impact of IGF-1 and IGF-1R expression among different cancer types was reported." (PMID 34804946, 2021). "IGF-1 and IGF-1R displayed inconsistent gene expression levels among diverse cancer cell lines." (PMID 34804946, 2021). "In this study, we investigated whether PKM2 can regulate IGF-1R expression and IGF-1R-mediated cancer cell survival, particularly under hypoxic conditions." (PMID 34359752, 2021). "Therefore, molecular targeted therapy for IGF1R has also become an attractive cancer treatment direction." (PMID 34093664, 2021). "Hence, PKM2 contributes to maintaining IGF-1R expression and cancer cell viability by regulating the interaction between IGF-1R and HSP90." (PMID 34359752, 2021). "Blocking the IGF1R via antisense therapy, anti IGF1R antibodies, dominant negative IGF1R, and small-molecule inhibitors has proven efficacious in the treatment of various cancers." (PMID 34234737, 2021). "A series of drugs targeting IGF-1/IGF1-R in the treatment of cancer are in clinical trials." (PMID 34804946, 2021). "Additionally, we have shown that PKM2 promotes cancer cell survival through the regulation of IGF-1R expression in hypoxic conditions." (PMID 34359752, 2021). "IGF1R is frequently overexpressed in a wide variety of human cancers, and IGF1R signaling may play a role in oncogene-induced cancer transformation in certain cancers." (PMID 32033461, 2020). "However, in confluent migratory cancer cells (with evident high levels of cell-cell contact), and under conditions where cells are unable to migrate, the IGF-1R remains in the Golgi apparatus." (PMID 33584548, 2020). "The spatial distribution of receptors and the bypassing of ligands could, however, substantially affect the success of such targeted therapies, which is exemplified by the apparent failures of IGF-1R inhibitors in cancer patients." (PMID 32458278, 2020). "This raises the possibility of targeting IGF-1R signaling in cancer treatment." (PMID 33511137, 2020). "Another way to target IGF-1R signaling in cancer could be eliminating cancer stemness or CSCs by inhibiting IGF-1R given that the IGF-1R pathway plays a crucial role in supporting stemness activities in cancer cells with stemness-related properties." (PMID 33511137, 2020). "In addition, the correlation of IGF1R expression levels with the progression of cancer and metastatic phenotypes has been reported." (PMID 32033461, 2020). "Furthermore, an increase in IGF1R signaling in response to IGFBP3 downregulation has been indicated as a possible resistance mechanism in cancer treatment." (PMID 33260481, 2020). "Again, activation of IGF-1R signaling was also observed in cancer cells exposed to ionizing radiation and depletion of IGF-1R or pharmacological inhibition of IGF-signaling increased cellular radiosensitivity by attenuating DSBs repair by homologous recombination (HR) and NHEJ, as well." (PMID 31948066, 2020). "This delay in M-phase progression may contribute to IGF1R inhibitor-induced suppression of cancer cell proliferation." (PMID 32033461, 2020). "Altered IGF-1R signaling contributes to several pathological conditions including cancer." (PMID 32458278, 2020). "Furthermore, how is the dual role of IGF-1R-mediated stemness controlled between the development of embryos and cancers?" (PMID 33511137, 2020). "This kinase could also be involved in the regulation of basal insulin secretion, especially because IGF1R inhibition has been shown to activate YES proteins in cancer cells." (PMID 32934005, 2020). "Overexpression of insulin growth factor receptor type 1 (IGF-1R) is observed in many cancers." (PMID 33122707, 2020). "IGF1R is known to play an important role in cancer development and progression." (PMID 32150843, 2020).
cancer (continued). "A study of the hEb peptide in BC, in vivo and in vitro, supports the hypothesis of IGF1R-independent hEb peptide action and biological activity against cancer cells." (PMID 32977489, 2020). "Therefore, if IGF-1R trafficking to and signaling from intracellular compartments determines its activity in cancer and contributes to an aggressive cancer behavior, it is now important to identify the molecular regulators of IGF-1R trafficking." (PMID 33584548, 2020). "We speculate that PSPC1 overexpression in tumors could be a potential biomarker for suggestion of cancer patients to receive treatment of IGF1R inhibitor." (PMID 32570949, 2020). "IGF-1R also regulates cancer stemness through other downstream pathways." (PMID 33511137, 2020). "Although an IGF1R mAb temprotumumab has been approved for the treatment of thyroid-associated ophthalmopathy, there is no trial of this agent for cancers." (PMID 32665850, 2020). "Given that both compounds, BMS and OSI, are inhibitors of IGF-1R tyrosine kinase activity, we set to assess whether their observed differential effects on cancer cell lines were attributable to their possible ability to inhibit off-target protein kinases." (PMID 33322337, 2020). "As the phosphoinositide 3-kinase (PI3K) pathway may trigger the transduction responses mediated by the IGF-1/IGF-1R system in cancer cells, we asked whether the PI3K/AKT signaling is involved in the activation of FAK in TNBC cells." (PMID 32325700, 2020). "IRA homodimers and IRA/IGF1R heterodimers have mitogenic actions and stimulate cancer cell growth." (PMID 32226608, 2020). "Therefore, IGF1R signaling pathway inhibitors have been utilized as alternative strategies for the treatment of drug-resistant cancer cells and to counteract drug resistance." (PMID 32371878, 2020). "Extensive molecular profiling revealed that a number of components of the IGF signaling pathway, including insulin receptor substrate-2 (IRS2) and IGF-binding protein-5 (IGFBP5) among others, play key roles in determining the sensitivity of cancer cells to a humanized IGF1R antibody." (PMID 32391121, 2020). "IGF-1R plays a key role in the proliferation, transformation and survival of various cancer cells." (PMID 32340152, 2020). "Second, upregulation of PSPC1 and IGF1R as well as their downstream signaling are known to activate epithelial to mesenchymal transition (EMT), stemness, and metastasis in association with poor prognosis of cancer patients." (PMID 32570949, 2020). "Therefore, more studies are needed to evaluate the efficacy of (short-term) fasting as an adjunct to IGF1R treatment in patients with cancer." (PMID 33260481, 2020). "In the following sections, we target IGF-1R signaling as a basis to explore how key signaling pathways are modulated in diverse conditions as well as the possible switches in controlling the double-bladed role of IGF-1R signaling in stem cells, CSCs, or cancer reprogramming." (PMID 33511137, 2020). "In addition to their role in these cancers, a cross-talk between IGF-1R and other growth factor receptors, notably epidermal growth factor receptors (HER family) has been implicated in the development of resistance to targeted therapies." (PMID 33122707, 2020). "Therefore, to minimize the influence on the normal physiological functions of IGF1R, the cancer cell-specific downstream targets and signaling pathways of IGF1R must be studied." (PMID 32971893, 2020). "However, the fact that these inhibitors have been largely unsuccessful in clinical trials renewed attention on how regulation of IGF-1R internalization, subcellular location and signaling are controlled in normal and cancer cells." (PMID 33584548, 2020). "The differential molecular mechanisms of cell death induction evoked by BMS and PPP (another IGF-1R inhibitor) on the same cellular models open the possibility to find a new therapeutic target for poor prognosis cancers based on these molecular mechanisms of cell death." (PMID 33322337, 2020).
cancer (continued). "Since BMS has an important antineoplastic effect on these poor prognosis types of cancer, these compounds could be taken in consideration for treatment independently of IGF-1R status." (PMID 33322337, 2020). "Furthermore, incubation with the Aurora B inhibitor ZM447439 potentiated the IGF1R inhibitor-induced suppression of cell proliferation, opening up new possibilities for more effective cancer chemotherapy." (PMID 32033461, 2020). "Since BMS has an important antineoplastic effect on these poor prognosis types of cancer, this compound could be taken into consideration for treatment independently of IGF-1R status." (PMID 33322337, 2020). "It is well documented that the MAPK signaling cascade bridges the crosstalk between ECM-mediated extracellular signaling through growth factors and their receptors such as IGF-1/IGF-1R, and subsequent intracellular response to allow cancer cell proliferation and migration." (PMID 32660466, 2020). "Furthermore, it is of cardinal relevance to generate evidence-based proof of potential benefits of multi-targeted cancer therapy as compared to IGF1R-directed monotherapy." (PMID 32391121, 2020). "IGF1/IGF1R signaling is therefore an attractive therapeutic target for cancer." (PMID 32033461, 2020). "Furthermore, the Aurora B inhibitor enhanced IGF1R inhibitor-induced suppression of cell proliferation, suggesting a potential for simultaneous use of IGF1R and Aurora B inhibitors in novel approaches to cancer chemotherapy." (PMID 32033461, 2020). "The fact that IGF-1R signaling promotes and maintains stemness in both stem cells and CSCs or cancer reprogramming raises the following questions: What transforms IGF-1R signaling from a traditional pathway to being central to the regulation of stem cell properties?" (PMID 33511137, 2020). "DNA fiber analysis revealed that IGF1R activation could rescue stalled DNA replication forks, but only in cancer cells with baseline IGF1R/PCNA interaction." (PMID 32701997, 2020). "Indeed, a combined inhibition of IGF-1R and the Src family kinases have been shown to enhance antitumor effects in various cancers by decreasing the activated survival pathways." (PMID 32340152, 2020). "Correlating IGF-1R location and activity at the Golgi or in the nucleus with a specific subset of cancer may be a valuable biomarker for targeting IGF-1R in cancer." (PMID 33584548, 2020). "By looking at its functions exclusively in cancers, IGF1R activation works coordinately with several downstream pathways including PI3K/AKT, Ras/Raf/MAPK and STAT to induce oncogenic transformation, cellular outgrowth, apoptotic resistance, migration, metastasis and angiogenesis." (PMID 32549375, 2020). "CDK6 and IGF1R are important regulators of cancer progression." (PMID 33219221, 2020). "Conversely, IGF-1R, one target of let-7, has been shown to be commonly overexpressed in cancer." (PMID 31847392, 2019). "Some studies have demonstrated that IR and IGF-1R are overexpressed in cancer stem cells." (PMID 30987250, 2019). "This might indicate that the drug targets of AEW541, namely receptors IGF1R and Insulin receptor, are connected to a vulnerable area within the metabolic pathways active during the development of both cancer types." (PMID 31208363, 2019). "Hence reports of IGF-1R activity in GD strongly correlates with the addition of these cancer potentiating molecules in the cellular microenvironment." (PMID 30881358, 2019). "Moreover, inhibition of Igf-1r can reverse mechanical allodynia and thermal hyperalgesia in a rat model of cancer bone pain." (PMID 31291762, 2019). "Moreover, IR-A overexpression in cancer cells is a major factor contributing to resistance to insulin growth factor 1 (IGF1) receptor (IGF1R) specific inhibitors, which are only marginally effective in cancer therapy when used as single therapy." (PMID 31480557, 2019). "Considering the key role of lncRNAs in drug resistance in cancer, we hypothesized that IGF-1R is regulated by lncRNAs." (PMID 31166382, 2019).